CRP (C-reactive protein)
Diseases named in the same sentence as CRP in open-access papers (continued):
Sharing a sentence is not in itself a finding about the gene and the disease.
glioblastoma (14 papers, 2017 to 2025). The most malignant astrocytic tumor (WHO grade IV). "Hypoxia and necrotic tumor cell-induced mediators are thought to be the reason for systemic inflammation, causing elevated CRP and reduced albumin levels in any cancer type, including Glioblastoma Multiforme." (PMID 40641926, 2025). "On the other hand, it was considered that CRP could be associated with the immunity which shifted to the paths of apoptosis and necrosis and this immunity could cause to the formation of Th2 mediated response in patients with glioblastoma." (PMID 33584142, 2021). "The WBC count, CRP/albumin ratio, and Ki-67 parameters can be used to predict 1-year overall survival in patients with glioblastoma multiforme." (PMID 40641926, 2025). "Approximately 25% of glioblastoma patients exhibit elevated CRP levels, correlating with reduced overall survival." (PMID 40420174, 2025). "In the present study, we developed novel hybrid nanoparticles of CRP polymer and 4F‐angiopep‐2 fusion peptide‐modified liposomes that enable efficient intracerebral Cas9 and sgRNA delivery for glioblastoma therapy." (PMID 38923275, 2024). "Rezultati izučavanja su pokazali da vrednosti CRP mogu biti prediktivni marker pri razdvajanju metastatskog tumora mozga od glioblastoma." (PMID 33584142, 2021). "In present study, serum CRP level in patients with glioblastoma was found to be in its laboratory reference interval, but it was found to be significantly elevated in patients who had solitary intracranial metastasis." (PMID 33584142, 2021). "The CRP levels of METASTASIS group (143.10 mg/L) were higher than those of GLIOMA group (23.90 mg/L); and it was 82% sensitive and 75% specific in distinguishing metastatic brain tumor from glioblastoma if CRP value was >55.00 mg/L." (PMID 33584142, 2021). "We investigated the prognostic impact of C-reactive protein to albumin ratio (CRP/Alb) on the survival outcomes of newly diagnosed glioblastoma multiforme (GBM) patients treated with radiotherapy (RT) and concurrent plus adjuvant temozolomide (TMZ)." (PMID 32566124, 2020). "Indeed, both CRP and fibrinogen, markers of inflammation, were found to predict OS in patients with glioblastoma." (PMID 40504312, 2025). "Nivoi CRP su bili viši u grupi sa metastazom (143,10 mg/L) nego u grupi sa gliomom (23,90 mg/L; ako su vrednosti bile veće od 55,00 mg/L CRP je bio 82% osetljiviji i 75% specifičniji za razdvajanje metastaza tumora mozga od glioblastoma." (PMID 33584142, 2021). "The Logistic Regression test revealed that CRP value could be the best laboratory parameter in distinguishing the solitary brain metastasis from the glioblastoma (B = 0.202, Wald = 4.353, p = 0.037)." (PMID 33584142, 2021). "Study results demonstrated that CRP values could be predictive biomarker in distinguishing metastatic brain tumor from glioblastoma." (PMID 33584142, 2021). "At the end of this study, it was considered that CRP level values measured preoperatively in blood serum of patients with solitary intracranial tumor could be a strong predictive biomarker in distinguishing metastatic brain tumor from glioblastoma." (PMID 33584142, 2021). "In addition, it has been shown that CRP levels may be elevated in the serum of the patients with glioblastoma and serum CRP may be a poor predictive biomarker of prognosis in glioblastoma, independently." (PMID 33584142, 2021). "Furthermore, CRP was significantly upregulated on the gene level in patients with glioblastoma." (PMID 28880870, 2017). "The ROC-Curve test demonstrated that if the CRP level value was measured greater than 55.00 mg/L, it could be 82% sensitive and 75% specific in distinguishing the solitary brain metastatis from the glioblastoma (area = 0.877, p = 0.001, cut-off value = 55.00 mg/L)." (PMID 33584142, 2021). "On the other hand, CRP was also found with very high amounts in glioblastoma tumor tissue and it did not change the serum CRP level, and that CRP was thought to be of tumor origin." (PMID 33584142, 2021).
Hypomagnesemia (14 papers, 2016 to 2026). An abnormally decreased magnesium concentration in the blood. "Emerging evidence indicates a significant inverse correlation between serum magnesium levels and high-sensitivity C-reactive protein (hs-CRP) concentrations, and hypomagnesemia is independently associated with elevated CRP." (PMID 41377556, 2025). "A diet low in Mg and hypomagnesemia are inversely correlated with elevated serum levels of C-reactive protein (CRP), which serves as an early marker of the inflammatory process in the body." (PMID 39769039, 2024). "Hypomagnesemia correlated significantly with elevated CRP levels (p = 0.0012), higher creatinine (p = 0.028), and lower eGFR (p = 0.017)." (PMID 39796484, 2024). "Hypomagnesemia contributes to oxidative stress and inflammation and is inversely related to CRP." (PMID 35889897, 2022).
oesophageal cancer (14 papers, 2005 to 2025). "According to certain studies, serum CRP concentration before treatment can be a predicted factor of curative response toward neoadjuvant CRT among local advanced esophageal carcinoma patients." (PMID 35898885, 2022). "In this multivariate survival analysis on patients with oesophageal cancer, CRP/Albumin ratio >0.50 was shown to be related to a statistically significant worse overall survival (HR: 2.44 95% CI 1.82–3.26 p < 0.0001)." (PMID 29196718, 2017). "There have been three previous studies from Japan that have shown the prognostic value of an elevated C-reactive protein concentration in patients undergoing resection for oesophageal cancer." (PMID 16685271, 2006). "An elevated serum C-reactive protein concentration, before surgery, has previously been shown to have independent prognostic value in patients with resectable oesophageal cancer." (PMID 16685271, 2006). "In the oesophageal cancer cohort, the CRP-spike, CRP-flat, and CRP-increase subgroups included 13, 27 and 31 patients, respectively, and multivariate analysis for PFS also identified CRP-spike (HR = 0.28, P = 0.0044) as an independent favourable prognostic factor." (PMID 39516365, 2023). "Additionally, some studies have reported the utility of serum CRP levels for predicting postoperative inflammatory complications of oesophageal cancer before any clinical signs or symptoms appear." (PMID 32252738, 2020). "Therefore, the results of the present study are consistent with C-reactive protein, measured before surgery, having prognostic value independent of established pathological criteria in patients with resectable oesophageal cancer." (PMID 16685271, 2006). "Similarly, a study from Japan has identified a shortened survival in oesophageal cancer patients with an elevated serum C-reactive protein (CRP) at the time of diagnosis." (PMID 17088911, 2006). "It was of interest that the threshold for C-reactive protein (>10 mg l−1), which we established in previous studies in patients with gastro-intestinal cancer, was superior to that (>5 mg l−1) used in previous prognostic studies in oesophageal cancer." (PMID 16685271, 2006). "CRP has been suggested as a useful prognostic indicator in esophageal carcinoma." (PMID 16117833, 2005). "Meta-analysis also demonstrated that esophageal carcinoma patients with a medium or high level of CRP had much worse OS than those of normal CRP; thus, we speculate that patients with normal pretherapeutic CRP levels will benefit more from the nimotuzumab treatment." (PMID 35898885, 2022). "In conclusion, CRP kinetics could be useful for predicting the prognosis of ICI treatment in patients with gastric and oesophageal cancer." (PMID 39516365, 2023). "Whilst this study has validated pre-treatment dNLR as a potential prognostic biomarker for oesophageal cancer patients treated with dCRT, analysis of other haematological components, albumin and other markers of the systemic inflammatory response such as C-reactive protein (CRP) was not conducted." (PMID 28893415, 2017).
proctitis (14 papers, 2015 to 2025). An inflammatory process affecting the anus. "In UC, CRP was highest extensive patients and lowest in proctitis group, and it similarly increased with disease activity." (PMID 40667420, 2025). "In the proctitis group, the median CRP was 4.6 mg/L (IQR: 4.1), and the median FCP was 333 μg/g (IQR: 892)." (PMID 39451607, 2024). "A most compelling argument in support of the continuum of the CRP process is that most long-term studies have demonstrated that acute radiation proctitis precedes the chronic phase and the initial proctitis severity often predicts the development of CRP." (PMID 39132647, 2023). "In our study, the irradiated mouse showed histological damage and continuous inflammation in the colorectal lesion, with increased plasma CRP levels, which are similar to that observed in patients with radiation proctitis." (PMID 32164317, 2020). "On the other hand, none of the examined blood biomarkers showed a correlation with Mayo endoscopic subscore in the proctitis group, while weak correlations of several biomarkers (CRP, WBC, ESR, PLT and Alb) with Mayo endoscopic subscore were found in left-sided colitis and extensive colitis cases." (PMID 31138962, 2019). "MLRS were adjusted for covariates including age-binary variable, sex, BMI-binary variable, disease duration-binary variable, current cigarette smoker, MCS category, Disease extent > proctitis, MCS, MES-binary variable, ALB, FC, CRP, and >1 advanced therapy class failure (biologic or small molecule)." (PMID 41208873, 2025). "Additionally, with respect to the site of involvement in patients with UC, the IL-6 (P = 0.597), CRP (P = 0.076), and hepcidin (P = 0.968) levels were not significantly different between patients with proctitis, left-sided colitis, and extensive colitis." (PMID 25628652, 2015). "Several studies have also demonstrated that CRP was only effective in monitoring endoscopic activity in extensive UC but not in proctitis or left-sided UC, suggesting that the efficacy of CRP may be insufficient in identifying endoscopic activity in patients with non- or mild clinical symptoms." (PMID 40289639, 2025). "However, despite the correlation of FCP with an inflammatory load similar to CRP, we could not demonstrate a significant difference between FCP levels in patients with proximal extension when compared with active proctitis." (PMID 39451607, 2024).
systemic vasculitis (14 papers, 2010 to 2025). "In addition, plasma PD-L1 levels were strongly associated with CRP titer in patients with systemic vasculitis." (PMID 34625602, 2021). "The main pathology of KD is a systemic vasculitis of the median and small blood vessels, as evident from the high levels of inflammatory parameters like CRP, WBC count, and the percentage of neutrophils found in the acute phase." (PMID 35989868, 2022). "As a result, systemic vasculitis in the skin, kidney, nerve, nasal cavity, and lung occurs along with the increased CRP in EGPA." (PMID 32770271, 2021). "CRP elevation is also suggestive of systemic vasculitis in patients with a poorer prognosis." (PMID 37362407, 2023). "By contrast, both CD4+ and CD8+ T-cells were proliferating in the affected skin, with both containing cytotoxic granzyme B. In addition, our data have demonstrated that plasma sPD-L1 was positively correlated with CRP levels in patients with systemic vasculitis." (PMID 34625602, 2021). "Notably, plasma soluble PD-L1 levels were increased, and these correlated with C-reactive protein in patients with systemic vasculitis." (PMID 34625602, 2021). "Based on CT abdomen findings, further workup for systemic vasculitis revealed elevated erythrocyte sedimentation rate (ESR), c-reactive protein (CRP), alkaline phosphatase, hemoglobin 16.7, and hematocrit 50.9, but showed negative antibodies." (PMID 38911052, 2024). "In a study of patients with systemic vasculitis, PWV, Aix, and CRP were found to be significantly higher in the active disease group compared to healthy controls." (PMID 32421279, 2020). "Serological markers such as CRP and von Willebrand factor are possible indicators of endothelial injury in systemic vasculitis but may not reflect the activity in isolated organ disease." (PMID 21672251, 2011).
ureteral stone (14 papers, 2017 to 2026). "In studies using serum markers of inflammation to predict the outcome of urinary stone cases, the number of leukocytes, neutrophils, CRP, and neutrophil-to-lymphocyte ratio were associated with the spontaneous passage of ureteral stones." (PMID 38327930, 2024). "Serum CRP measurement emerges as a promising new biomarker for predicting ureteral stone presence, offering potentially more accurate diagnostic insights." (PMID 39036228, 2024). "While no previous studies have specifically evaluated the diagnostic accuracy of PLR or MPV for ureteral stone passage, other studies have identified alternative variables, such as stone size, location, and CRP levels, as significant predictors of spontaneous stone expulsion." (PMID 41346883, 2025). "An obstructing ureteral stone can cause inflammation, and CRP levels increase." (PMID 35464554, 2022). "In addition, it aims to evaluate the potential utility of GDF-15 in predicting the spontaneous passage of ureteral stones measuring 2–10 mm, and to assess its association with other predictive factors such as ureteral wall thickness, serum CRP, and hematological parameters." (PMID 41515626, 2026). "We aimed in our study to determine the potential predictive value of different NCCT parameters and acute phase markers (ESR and CRP) for identifying impacted ureteric stones preoperatively." (PMID 41509097, 2026). "Recently, the serum CRP level has been studied as a possible predictor for SSP in patients with ureteral stones." (PMID 39036228, 2024). "Lower CRP levels (≤6 mg/L), along with other factors like demographics and lab results, suggest a better chance of naturally passing symptomatic lower ureteric stones (5 mm-10 mm)." (PMID 39036228, 2024). "Therefore, a comprehensive study was conducted, examining factors like WBC count, neutrophil count, urine specific gravity, leukocyturia, hematuria, and indicators, primarily CRP, to determine their predictive value in the spontaneous passage of lower ureteric stones." (PMID 39036228, 2024). "In suspected ureteral stone cases, laboratory work-up generally includes urinalysis, complete blood count (CBC), C-reactive protein (CRP), and renal function tests." (PMID 41515626, 2026). "Comparison of CRP levels between the observation and control groups in T2DM patients with complex ureteral stones (Mean ± SD)." (PMID 40761819, 2025). "In studies using serum inflammation markers to predict the impaction of ureteral stones, serum white blood cell (WBC), neutrophil count, c-reactive protein (CRP), and neutrophil-lymphocyte ratio (NLR) values were found to be related to the spontaneous passage of ureteral stones." (PMID 32306948, 2020). "In contrast to the results of previous studies, CRP was not an independent predictor of spontaneous ureteral stone passage in our study." (PMID 28593428, 2017). "Leukocytosis and elevated CRP levels may also be observed but are not specific to ureteral stones, as they may occur in various acute pathologies." (PMID 41515626, 2026).
acute lymphoblastic leukemia (13 papers, 2013 to 2025). Leukemia with an acute onset, characterized by the presence of lymphoblasts in the bone marrow and the peripheral blood. "The MEDAS score was significantly associated with lower CRP concentrations and higher adiponectin concentrations in childhood acute lymphoblastic leukemia survivors." (PMID 40043850, 2025). "Meanwhile, the ROC curve of Delta CRP for the diagnosis of all-cause infection showed an area under the ROC of 0.748 (p = 0.008)." (PMID 37189057, 2023). "These also mean that 25-(OH) D3 deficiency aggravates all-cause diseases, which is associated with the course of inflammation and infection but not CRP levels." (PMID 23878538, 2013). "Immunepotent CRP (ICRP), a bovine dialyzable leukocyte extract, displays selective cytotoxicity against several solid and hematologic cancers by inducing ROS-dependent apoptosis in T-cell acute lymphoblastic leukemia (T-ALL) cells, leading to nuclear and mitochondrial damage." (PMID 39063180, 2024).
amyotrophic lateral sclerosis (13 papers, 2013 to 2025). Amyotrophic lateral sclerosis (ALS) is a neurodegenerative disease characterized by progressive muscular paralysis reflecting degeneration of motor neurons in the primary motor cortex, corticospinal tracts, brainstem and spinal cord. "The study aims to investigate the effects of the ALDH2 rs671 (A) allele and high sensitivity C-reactive protein (hs-CRP) on the clinical phenotypes of amyotrophic lateral sclerosis (ALS) in male and female patients." (PMID 39290715, 2024). "Recently, an elevated CRP baseline was also linked to a faster progression of Amyotrophic Lateral Sclerosis (ALS) compared to patients with lower CRP baselines." (PMID 33673378, 2021).
Arterial thrombosis (13 papers, 2010 to 2025). The formation of a blood clot inside an artery. "Examining associations between MetS and laboratory and clinical CVD markers, we found that MetS was independently associated with CRP and UA as well as with arterial thrombosis, physical activity and atherosclerotic plaques, respectively." (PMID 36700208, 2022). "Our work showed that, aside from demographic parameters, ΔHR, resting HR, PAH, history of arterial thrombosis, CRP levels and HAQ-DI score are important factors associated with the 6MWD in SSc, while pulmonary interstitial and musculoskeletal involvements seem to have no major influence." (PMID 29246248, 2017). "The results showed that neutrophil and lymphocyte counts, Hb, CRP, IL-6, integrin β1, integrin β2, and integrin β3 levels were independent predictors of arterial thrombosis (p < 0.05)." (PMID 37998519, 2023). "Given the stronger association of sP-selectin with arterial thrombosis, combining elevated sP-selectin with CRP, calprotectin, and D-dimer levels could help predict the location of arterial thrombosis." (PMID 39661669, 2024). "In this study, we aimed to detect the major inflammatory markers C-reactive protein (CRP), IL-6 (a cytokine closely related to arterial thrombosis), integrin β1, integrin β2, and integrin β3 in patients with acute arterial thrombosis (specifically AMI) and acute VTE." (PMID 37998519, 2023). "The 6MWD was significantly and independently associated with gender, age, body mass index, baseline heart rate (HR), HR variation during the test, PAH, history of arterial thrombosis and C-reactive protein levels, as well as with the HAQ-DI score in a sensitivity analysis." (PMID 29246248, 2017). "In addition, CRP might represent a key link between vascular inflammation and arterial thrombosis or platelet activation." (PMID 30563269, 2018). "Although C-Reactive protein concentrations are a strong independent predictor of future vascular events, there has been no direct evidence that CRP variants contribute to cardiovascular disease phenotypes such as carotid intima-media thickness or arterial thrombosis." (PMID 20078877, 2010).